EPO (erythropoietin)
Diseases named in the same sentence as EPO in open-access papers (continued):
Sharing a sentence is not in itself a finding about the gene and the disease.
osteoporosis (10 papers, 2018 to 2025). A condition of reduced bone mass, with decreased cortical thickness and a decrease in the number and size of the trabeculae of cancellous bone (but normal chemical composition), resulting in increased fracture incidence. "The cause of osteoporosis is multifactorial and could be influenced by hypogonadism, increased erythropoietin (EPO) levels, bone marrow expansion, vitamin D and calcium deficiency." (PMID 30064480, 2018). "Because patients requiring EPO therapy are often prone to osteoporosis, our data advocate for using the lowest effective EPO dose for the shortest period of time to decrease thromboembolic complications and minimize the adverse skeletal outcome." (PMID 32471308, 2020). "Since EPO is widely used in clinical practice, especially in patients who are frequently prone to osteoporosis, further studies are warranted to explore the skeletal effects of this intervention in human patients." (PMID 32471308, 2020). "Therefore, considering that patients requiring EPO treatment are often susceptible to osteoporosis, it is crucial to administer the lowest effective EPO dose to mitigate the adverse consequences of osteoporosis exacerbation." (PMID 39835325, 2024). "The exact reason of osteoporosis in TI could be hypogonadism and/or an increase in erythropoietin (EPO) levels." (PMID 30064480, 2018). "However, the present study did not allow us to determine whether EPO has an effect on the link between hemoglobin and osteoporosis due to a lack of EPO measurements." (PMID 35414128, 2022).
ovarian carcinoma (10 papers, 2011 to 2022). A malignant neoplasm originating from the surface ovarian epithelium. "The similarity of EPO-GEMM ovarian cancers to human HGSOC was striking, given that our electroporation method does not discriminate between cell types within the targeted tissue." (PMID 35082152, 2022). "Future studies incorporating the flexible features of the EPO-GEMM approach will enable the further dissection of mechanisms that dictate ovarian cancer response and resistance and, more broadly, expedite investigation of other clinically relevant aspects of this disease." (PMID 35082152, 2022).
preeclampsia (10 papers, 2020 to 2025). Preeclampsia is a hypertensive disorder of pregnancy that is characterized by new-onset hypertension with proteinuria presenting after 20 weeks of gestation, and depending on mild or severe forms may initially present with severe headache, visual disturbances, and hyperreflexia. "The enrichment of 5′ genes associated with chimeric RNAs in preeclampsia within the cellular response to the erythropoietin pathway suggests the potential role of chimeric RNAs in regulating erythropoiesis in preeclampsia." (PMID 39397868, 2025). "The erythropoietin concentration was higher in the Ob group controlling for confounding variables such as ferritin, gestational age, underlying health conditions and pregnancy complications (gestational diabetes or preeclampsia)." (PMID 32244712, 2020). "The increase in nRBC among newborns from superimposed preeclampsia/eclampsia is most likely due to chronic placental hypoxia, which raises erythropoietin levels, leading to activated erythropoiesis in newborns." (PMID 38183053, 2024). "There are published data about the markers of chronic hypoxia (such as polycythaemia, erythropoietin, and nucleated red blood cells), which were elevated in the cord blood of fetuses born to women with preeclampsia." (PMID 37239851, 2023). "At the same time, recombinant erythropoietin used in doses that enhance erythropoiesis can lead to the development of preeclampsia." (PMID 32942669, 2020). "The administration of short-chain peptides mimicking the spatial structure of the B erythropoietin chain may become one of the directions of searching for new drugs for preeclampsia prevention and therapy." (PMID 32942669, 2020). "“Non-classical” activity of erythropoietin allows us to consider it as a therapeutic agent for the prevention of conditions associated with necrosis, apoptosis, and inflammatory processes in tissues, in particular, in the treatment of preeclampsia." (PMID 32942669, 2020). "Therefore, the focus of our study was aimed at estimating the miRNA expression profile of placental tissue and blood plasma in pregnant women with preeclampsia using deep sequencing and quantitative RT-PCR, as well as determining the concentration of erythropoietin." (PMID 32093169, 2020).
renal carcinoma (10 papers, 2007 to 2024). A carcinoma arising from the epithelium of the renal parenchyma or the renal pelvis. "EPO-positive staining was exhibited in the renal cancer cells and the cells lining the cyst wall, as shown by immunohistochemical analysis using an anti-EPO antibody." (PMID 25295086, 2014). "Erythropoietin was also involved in cell growth, invasion, survival, and sensitivity to the multikinase inhibitor sunitinib and cisplatin in renal cancer cells and in head and neck squamous cell carcinoma, respectively." (PMID 25426117, 2014). "It was subsequently discovered, however, that pVHL negatively regulates hypoxia-inducible genes such as vascular endothelial growth factor (VEGF) and erythropoietin (EPO) in renal cancer cell lines in vitro." (PMID 18047741, 2007). "This may be due to EPO release by destroyed cells into the blood stream following embolization, or the induction of EPO production by hypoxia in renal cancer cells and/or other renal cells, such as cyst epithelial cells." (PMID 25295086, 2014). "As to renal carcinoma, patients with low levels of KIAA0101 and EPO had a relative higher 3 and 5-year survival rate (KIAA0101: p = 0.0367, EPO: p = 0.0863)." (PMID 26575329, 2016). "Furthermore, the EPO-EPOR pathway stimulated the expression of cyclin D1 and inhibiting the expression of p21cip1 and p27kip1 through the phosphorylation of JAK2 and ERK1/2, led to a more rapid progression through renal cancer cell cycle." (PMID 25426117, 2014).
type 1 diabetes (10 papers, 2013 to 2025). "In a type 1 diabetic rat model (streptozotocin-induced), erythropoietin (EPO)-induced cardioprotection through RISK signaling was lost." (PMID 25525500, 2014). "In patients with type 1 diabetes and hypoglycemia unawareness, treatment with EPO is associated with a beneficial effect on cognitive function in a complex reaction time task assessing sustained attention/working memory." (PMID 23577069, 2013). "Also, a single dose of EPO has been shown to have beneficial effect on sustained attention/working memory in type 1 diabetic patients with hypoglycaemia." (PMID 30597853, 2018).
vitamin B12 deficiency (10 papers, 2013 to 2025). A disease characterized by low serum levels of vitamin B12, either inherited or acquired. "However, after excluding patients with (sub)clinical vitamin B12 deficiency and/or hypoxemia, WT group of patients exhibited significantly lower erythropoietin levels (p=0.015)." (PMID 39991164, 2025). "ESA hyporesponsiveness caused various clinical conditions including bleeding/blood loss, hematopoietic disorder (infection, inflammation, and malignant tumor), deficiency of elements required for erythropoiesis (iron, folic acid, and vitamin B12 deficiency), and anti-erythropoietin antibody." (PMID 30182223, 2019). "Additionally, canine erythropoiesis may be less sensitive to cobalamin deficiency due to different erythropoietin regulation." (PMID 39728438, 2024). "Second, we did not investigate the use of erythropoietin, iron or vitamin B12 deficiency, and reticulocyte count, which could have affected RDW values and, thus, might have limited the interpretation of study results." (PMID 24321201, 2013).
cardiomyopathy (9 papers, 2012 to 2024). A disease of the heart muscle or myocardium proper. "DOX-induced cardiomyopathy was reversed by the addition of erythropoietin and this cardioprotective mechanism by erythropoietin is mediated by the phosphorylation of ERK." (PMID 27195769, 2016). "The aim of the present study was to investigate the protective effect of carbamylated erythropoietin (CEPO) against cardiomyopathy in high-fat, high-carbohydrate diet-fed rats with streptozotocin (STZ)-induced diabetic cardiomyopathy (DCM)." (PMID 24137228, 2013). "It is reported that EPO restored and augmented extracellular signal-regulated kinase (ERK) activity and activated ERK phosphorylated GATA-4 to enhance its DNA binding and transcriptional activation in cardiomyopathy models." (PMID 22954171, 2012). "In addition they used specific inclusion criteria containing intradialytic hypotension, muscle cramping, lack of energy, muscle weakness or myopathy, cardiomyopathy, or lack of responsiveness to erythropoietin." (PMID 22720143, 2012).
colon cancer (9 papers, 2014 to 2022). "Our in vitro study demonstrated the beneficial effect of LFM-A13 in combination with erythropoietin on antitumor activity in both tested colon cancer cell lines." (PMID 29690619, 2018). "We explored the effect of exogenous erythropoietin on proliferation of both the colon cancer cells DLD-1 and Ht-29." (PMID 27543111, 2016). "The expression of VEGF and EPO involved in colon cancer cells proliferation, angiogenesis, invasion and metastasis." (PMID 27144516, 2016). "Next, we wanted to confirm the dual nature of effect of erythropoietin on different colon cancer cell lines." (PMID 27543111, 2016). "Erythropoietin has been reported to stimulate tumor growth in EpoR-expressing tumors such as breast, cervical, endometrial, gastric, and colon cancer." (PMID 27543111, 2016). "We investigated whether erythropoietin can enhance in vivo colon cancer cell growth and examined the pharmacodynamics features of the promising combination in DLD-1 and HT-29 xenografts." (PMID 29690619, 2018). "Erythropoietin also supports survival of endothelial cells, neurons subjected to hypoxia, and thereby greatly supports survival of tumor cells such as breast cancer, head and neck, and colon cancer cells." (PMID 27543111, 2016). "Since EPO was induced by HIF-1α, we further examined whether vanillic acid suppressed EPO and VEGF transcription in human colon cancer HCT116 cells." (PMID 30678221, 2019). "Naturally, the overexpression of HIF-1α upregulated VEGF and EPO protein and mRNA levels in the cells (lane 5), silencing of HIF-1α abolished the upregulation of VEGF and EPO protein and mRNA levels mediated by ZFP91 (lane 4), supporting that ZFP91 is able to upregulate HIF-1α in colon cancer cells." (PMID 27144516, 2016).
experimental autoimmune encephalomyelitis (9 papers, 2008 to 2026). An autoimmune demyelinating disease of the central nervous system that is produced experimentally in animals by the injection of homogenized brain or spinal cord in Freund's adjuvant. "Another study found that treatment with EPO led to an increase in the number of Tregs in the spleen and lymph nodes of mice with experimental autoimmune encephalomyelitis (EAE)." (PMID 40131554, 2025). "Along these lines, an EPO-mediated reduction in Th17 cells was also presented in an experimental autoimmune encephalomyelitis mouse model." (PMID 27481313, 2016). "For instance, EPO inhibits pro-inflammatory cytokine release and T cell responses in experimental autoimmune encephalomyelitis (EAE)." (PMID 25324845, 2014). "In experimental autoimmune encephalomyelitis (EAE) treatment with EPO reduces the clinical score, reduces the demyelination and protects from axonal loss." (PMID 22043313, 2011). "Similarly, in vitro models of MS, including experimental autoimmune encephalomyelitis and experimental autoimmune neuritis, demonstrate endogenous EPO induction in both the CNS and the peripheral nervous system." (PMID 41602576, 2026). "Potent beneficial immunomodulatory and anti-inflammatory effects of whole-molecule erythropoietin have been demonstrated in a variety of animal disease models including experimental autoimmune encephalomyelitis (EAE); however, excessive hematopoiesis limits its use in clinical applications." (PMID 32959273, 2021). "EPO exhibits neurotrophin-like properties, and axon protection is most effective when EPO is combined with high-dose methylprednisolone, as observed in a rat model of myelin oligodendrocyte glycoprotein (MOG)-induced experimental autoimmune encephalomyelitis." (PMID 35052875, 2022).
head and neck cancer (9 papers, 2007 to 2024). A primary or metastatic malignant neoplasm affecting the head and neck. "In a double-blind, placebo-controlled study, Henke and colleagues reported a poorer outcome for head and neck cancer patients who were treated with EPO." (PMID 23305401, 2013). "Neverthelss, a prospective, randomized-controlled trial of 351 patients with head and neck cancers found that patients who received erythropoietin to achieve Hb levels higher than 140 g/L (women) or 150 g/L (men) had poorer locoregional progression-free survival than those who received placebo." (PMID 29661211, 2018). "However, more recent studies have shown that EPO treatment may have different results in breast cancer and head and neck cancer." (PMID 22639817, 2012).
Hypoalbuminemia (9 papers, 2007 to 2024). The concentration of albumin in the blood circulation is below the lower limit of normal. "Generally, lower weight and hypoalbuminemia indicate associated protein-energy malnutrition that induces inflammation and erythropoietin hyporesponsiveness." (PMID 35746954, 2022). "Elevated levels of proinflammatory cytokines led to inadequate production of erythropoietin, impaired erythrocyte maturation, a poor nutritional status (hypoalbuminemia), and increased levels of hepcidin and oxidative stress." (PMID 33158258, 2020). "Secondly, factors such as toxin accumulation, shortened red blood cell lifespan, and insufficient erythropoietin secretion due to CKD-related reasons suggest a close relationship between red blood cell levels and hypoalbuminemia and kidney disease progression in patients with CKD." (PMID 39545043, 2024).
lung diseases (9 papers, 2018 to 2026). "Consequently, hypoxemia due to SARS-CoV-2-infection-associated lung disease is a key trigger of EPO production." (PMID 36842152, 2023). "Secondary erythrocytoses are most often acquired and can result from an adaptive response to hypoxia that stimulates erythropoietin (EPO) secretion, from heart and lung diseases, or from some EPO-secreting tumors." (PMID 35052472, 2022). "In the last 20 years, erythropoietin (EPO)—the main erythropoietic hormone—has emerged as an important cytoprotective cytokine in several tissues, including the brain, heart, spinal cord, kidneys and lungs, in animal models of pulmonary diseases." (PMID 39338226, 2024). "No published research has studied the impact of EPO on the morbidity or mortality of patients with pulmonary fibrosis, and very little information is known in the context of other lung diseases such as chronic obstructive pulmonary disease." (PMID 39338226, 2024). "Moreover, determination of erythropoietin (EPO) levels can be helpful for differential diagnosis, as patients with lung diseases and hypoxemia can also develop secondary polyglobulia." (PMID 29492207, 2018).
pancreatic cancer (9 papers, 2007 to 2025). "This approach enabled the detection of the expression of two pancreatic cancer biomarkers, live erythropoietin-producing hepatocellular A 2 (EphA2), and epithelial cell adhesion molecule (EpCAM)." (PMID 40284444, 2025). "Erythropoietin L-2HG can be produced by LDHA in hypoxic settings to maintain the proper balance of pancreatic cancer stem cell differentiation." (PMID 37391503, 2023). "However, protection of cortical neurons, pancreatic cancer cells, and retinal photoreceptors require HIF-1α, which is generally associated with upregulation of protective growth factors such as VEGF (vascular endothelial growth factor) and EPO (erythropoietin)." (PMID 19461932, 2009). "First, neither CSPG4low HPDE cells nor pancreatic cancer cell lines showed significant elevation of CSPG4 expression, although hypoxia greatly increased expression of other hypoxic markers, such as BNIP3, EPO (data not shown), and NIX." (PMID 24932730, 2014).
parasitemia (9 papers, 2012 to 2025). "Blood transfusion rescued body weight loss, decreased parasitemia, and reduced serum erythropoietin levels." (PMID 40590713, 2025). "In a P. yoelii mouse model, treatment with an oral ferroportin inhibitor, VIT-2763 (Vamifeport) increased parasitemia, accompanied by increased levels of pro-inflammatory cytokines, erythropoietin, and liver injury markers." (PMID 40871363, 2025). "The activation of EPO signaling was measured at the peak of parasitemia in infected and reinfected mice." (PMID 38892340, 2024). "An increase in parasitemia level can cause destructions (hemolysis) of infected and non-infected RBCs, erythropoietin suppression, and dyserythropoietic." (PMID 35974350, 2022). "We believe the immune response to parasite infection and physical challenge required by migration was possibly the causative factor, once these birds went through an acute hypoxic event (drowning) that was not long enough to increase erythropoietin production." (PMID 32448250, 2020). "The following factors may be related to the high variation in parasitemia, i.e. genetic background of the donor, the quality of the hematopoietic stem cells, the efficiency of the hydrodynamic injection and therefore the IL-3/EPO expression." (PMID 26098918, 2015). "In this study, EPO treatment also reduced parasitemia and may thus introduce bias." (PMID 24995009, 2014). "In mice infected with Plasmodium berghei, EPO administration does not substantially influence parasitemia, but significantly prolongs the survival." (PMID 22094132, 2012). "However, in previous works the effect of EPO was prominent without changed parasitemia." (PMID 24995009, 2014).
prostate carcinoma (9 papers, 2013 to 2025). A carcinoma that arises from epithelial cells of the prostate gland. "The production of and responsiveness to EPO, which are essential for maintaining bone homeostasis, may also be implicated in vertebral fractures in patients with advanced prostate cancer characterized by a highly inflammatory condition." (PMID 40647430, 2025). "Based on its high expression in castration-resistant prostate cancer (CRPC), we herein develop a CRISPR-Cas9-based genome-editing nanomedicine to target erythropoietin producing hepatocyte receptor A2 for the treatment of castration-resistant prostate cancer." (PMID 36588949, 2022). "In the literature, a case is presented about FCH PET/CT in a patient with biochemical recurrent prostate cancer who was receiving erythropoietin for hemochromatosis." (PMID 33374148, 2020).